TRPV1 (transient receptor potential cation channel subfamily V member 1)
Diseases named in the same sentence as TRPV1 in open-access papers (continued):
Sharing a sentence is not in itself a finding about the gene and the disease.
cystitis (18 papers, 2012 to 2025). Inflammation of the urinary bladder. "The induced cystitis was associated with increased TRPV1 channel activity in neurons innervating the bladder and the associated dorsal root ganglia, along with increased TRPV1 expression in the bladder." (PMID 24861977, 2014). "TRPV1 contributes to the development of mechanical and thermal hyperalgesia and is known to be upregulated in cystitis." (PMID 37701183, 2023). "Earlier work provided evidence for the role of sensory TRP channels in bladder hyperreactivity during cystitis (TRPV1 and TRPA1), the detection of noxious stimuli in the bladder (TRPA1), and cold-induced bladder reflexes (TRPM8)." (PMID 35008533, 2021). "Overall, these data indicate that TRPV1 plays a principal role in the development of pain related to cystitis, suggesting the utility of TRPV1 blockers to treat this condition." (PMID 24861977, 2014). "Cystometry during infusion of saline, 100 μM capsaicin or 0.5% acetic acid showed that GRC-6211 (0.1 mg/kg) completely prevented capsaicin induced irritation, which suggests that TRPV1 antagonists might be useful for the treatment of cystitis." (PMID 36135835, 2022). "Indeed, AEA, via activation of TRPV1, contributes to hyperreflexia and hyperalgesia during cyclophosphamide-induced cystitis." (PMID 34290614, 2021). "In addition, the expression of TRPV1 on the urothelial cell surface, as well as its important role in bladder sensation and regulation during cystitis, has been well demonstrated previously." (PMID 26798205, 2015). "After induction of cystitis by injection of cyclophosphamide, we observed a robust increase of the functional responses to agonists of TRPM3, TRPV1, and TRPA1 in bladder-innervating DRG neurons." (PMID 35008533, 2021). "These TRP channels, like TRPV1, TRPV4, and TRPA1, contribute to normal voiding behavior and/or bladder hypersensitivity in experimental models of cystitis." (PMID 35008533, 2021). "In mice with CYP-induced cystitis, the proportion of WGA-AF555-labeled neurons responding to TRPM3, TRPV1, and TRPA1 agonists was significantly higher than in sham treated animals (p = 0.002, p < 10−6, and p = 0.02, respectively)." (PMID 35008533, 2021). "Chronic cystitis increased TRPA1 and TRPV4 transcripts in the (sub)urothelium of female rats, whereas in acute cystitis, TRPV1 and TRPV4 mRNA levels are decreased." (PMID 30087301, 2018). "However, TRPV1 and TRPV4 protein levels are increased in acute and chronic cystitis." (PMID 30087301, 2018). "Cystitis induced by cyclophosphamide (a chemotherapeutic agent) in mice and rats is characterized by mechanical bladder hyperactivity which is antagonized by pretreatment with selective TRPV1 antagonist SB-366791, and is not observed in TRPV1 null mice." (PMID 24861977, 2014). "We found that several MSC genes including Trpv1, Trpv4, Piezo1, and Piezo2 were all upregulated in both layers of the bladder (urothelium and detrusor), following chronic CYP-induced cystitis, but not acute CYP-induced cystitis." (PMID 35295484, 2021). "In a cyclophosphamide (CYP) model of cystitis, we found that the gene expression of several candidate MSCs (Trpv1, Trpv4, Piezo1, and Piezo2) were all upregulated in the urothelium and detrusor following chronic CYP-induced cystitis, but not acute CYP-induced cystitis." (PMID 35295484, 2021).
glioblastoma (18 papers, 2010 to 2025). The most malignant astrocytic tumor (WHO grade IV). "TRPV1 variant 3 mRNA expression reached significance (p = 0.0009) for survival with short OS glioblastoma patients, showing a lower TRPV1 variant 3 mRNA expression compared with long OS patients." (PMID 34458247, 2021). "In addition, the expression of 5'UTR TRPV1 variants as prognostic factor in the survival of glioblastoma patients was evaluated." (PMID 27829230, 2016). "Studies of their possible functions demonstrated that the vanilloid receptor TRPV1 triggers tumor cell death in glioblastoma cells." (PMID 33281564, 2020). "Specifically, glioblastoma cell lines have been demonstrated to be sensitive to TRPV1 agonists and to overexpress this receptor." (PMID 31261921, 2019). "However, TRPV1 mRNA levels are upregulated in the U373 glioblastoma line, high-grade astrocytes, “brain tumors,” and the RT4 renal cell carcinoma line; likewise, upregulated TRPV1 protein expression is observed in the U373 and RT4 cell lines." (PMID 32545311, 2020). "Finally, it has been recently reported at mRNA level, that TRPV1 was over-expressed in glioblastoma (GBM) patients with higher overall survival (OS, more than 12 months) as respect to those showing lower OS (less than 12 months)." (PMID 27829230, 2016). "Analysis of TRPV1 and TRPV2 expression showed that they are up-regulated in glioblastoma as compared to normal tissue." (PMID 33281564, 2020).
Hyperglycemia (18 papers, 2008 to 2025). An increased concentration of glucose in the blood. "Several studies show that hyperglycemia cause a dysfunction and down-regulation of TRPV1 in diabetic animals." (PMID 23607427, 2013). "Similarly, TRPV1 is a highly selective Ca2+ channel, which facilitates cigarette smoke-associated airway inflammation and opioid-induced hyperglycemia." (PMID 38014253, 2023). "Examples of potential mechanisms to explore include chronic low-grade inflammation and/or oxidative stress, PKC-induced transient receptor potential vanilloid 1 (TRPV1) overactivity caused by hyperglycemia, and changes in body weight and skeletal muscle mass and/or fiber type." (PMID 36703927, 2022). "This enhancement suggests that the PKA phosphorylation pathway is activated through TRPV1 signaling, further underscoring the therapeutic potential of CAP in combating endothelial dysfunction caused by hyperglycemia." (PMID 41226458, 2025). "In this study, we used OGTT to determine the effect of TRPV1 inactivation on hyperglycemia in Trpv1 KO and wild-type mice kept on HFD, a model of glucose intolerance." (PMID 31344877, 2019). "This demonstrates that the enhanced TRPV1-evoked Ca2+ responses are, at least in part, a hyperglycaemia-induced effect." (PMID 29930087, 2018). "Additionally, increased expression of UCP2 induced by TRPV1 exerted a protective antioxidant effect on the liver in non-alcoholic fatty liver disease and on vascular endothelium during hyperglycemia." (PMID 41226458, 2025). "A phenotype of hyperglycemia is described in mice lacking TRPV1 channels; however, the mechanism underlying this event remains an open question." (PMID 35806020, 2022). "In addition to inducing behaviorally expressed neuropathic thermal hyperalgesia and mechanical allodynia, STZ-induced hyperglycemia and DNP caused significantly increased expression of P2X3 and TRPV1 in the DRG." (PMID 32104520, 2020). "In the current study, we investigated the effect of TRPV1 blockade on hyperglycemia indirectly by assessing oral glucose tolerance (i.e., the ability to clear orally administered glucose), both as a direct measurement of blood glucose and the insulin response to oral glucose." (PMID 31344877, 2019). "In addition to wild type mice, we analyzed the responses to acute hypo- and hyperglycemia in transient receptor potential cation channel subfamily V member 1 (TRPV1) cell depleted mice." (PMID 32232099, 2019). "TRPV1 activation by capsaicin might protect against hyperglycemia-induced endothelial dysfunction through a mechanism involving the PKA/UCP2 pathway." (PMID 23607427, 2013). "We hypothesised that TRPV1 activation by capsaicin attenuates hyperglycemia-induced endothelial dysfunction through a UCP2-mediated antioxidant effect." (PMID 23607427, 2013). "The present study was undertaken to test the hypothesis that TRPV1 activation by capsaicin attenuates hyperglycemia-induced endothelial dysfunction through a UCP2-mediated antioxidant effect." (PMID 23607427, 2013). "Furthermore, hyperglycemia is known to induce oxidative stress, as a result a slight increase in ROS is known to activate transcriptional machinery enhancing the expression of TRPV1, at the same time higher levels of ROS can lead to neuronal cell death." (PMID 18312687, 2008). "Melatonin and selenium reduced hyperglycemia-induced excessive ROS release, apoptosis, and Ca2+ influx through inhibiting TRPM2 and TRPV1 channel activation in dorsal root ganglion and hippocampus of diabetic rats." (PMID 38308007, 2024). "Hyperglycemia did not induce robust vagus nerve responses, and deletion of TRPV1 nociceptors attenuated the hypoglycemia-dependent vagus nerve signals." (PMID 32232099, 2019). "This suggests that, at least in the early stages of hyperglycemia, the sensitization of sensory neurons do not depend on the increased expression of TRPV1 channels but rather on post-transcriptional modification involving ROS, PKC and Src kinases." (PMID 29474476, 2018).
Hyperglycemia (continued). "However, it was subsequently reported that STZ by itself had a direct effect on inducing sensory neuropathy by driving the expression of TRPV1 channels in neurons (sensory and spinal) and by activating microglia in the spinal cord, all of these effects were independent of hyperglycemia." (PMID 29474476, 2018). "Hyperglycemia, at 21 days, also increased protein expression of cystathionine-β-synthase enzyme (CBS) and TRPC6, but not TRPA1 nor TRPV1, channels in dorsal root ganglia (DRG)." (PMID 30602386, 2019).
lung carcinoma (18 papers, 2016 to 2026). "In mouse models deficient in TRPV1, both the neuronal excitability and bone pain associated with lung cancer were markedly reduced." (PMID 38567163, 2024). "We reported that SN excitation and bone pain associated with lung cancer are decreased in TRPV1−/− mice." (PMID 37461623, 2023). "A causal contribution of TRPV1 to the anti-invasive impact of R(+)-methanandamide on cervical and lung cancer cells was shown to be mediated by upregulation of TIMP-1." (PMID 31143113, 2019). "Therefore, we believe that the high expression level of TRPV1 mRNA is an independent risk factor for poor prognosis in lung cancer patient cohorts, and HR higher than 1 indicates that the mRNA expression of this gene could be a risk factor." (PMID 35620019, 2022). "From pancreatic to hepatocellular and then to lung cancer, the implications of TRPV1 intertwine deeply with tumor dynamics, therapeutic strategies, and pain management." (PMID 38567163, 2024). "Lung cancer-related studies have unveiled the profound effects of TRPV1 on sensory neuronal excitability and bone pain." (PMID 38567163, 2024). "The studies also showed the expression of CBD receptors CB1, CB2, and TRPV1 from the lung cancer cell lines as an entry point for CBD." (PMID 38891847, 2024). "Here, the authors identify autophagy-mediated EGFR hyperactivation by TRPV1 promotion as a mechanism of cisplatin resistance and demonstrate the efficacy of a TRPV1 inhibitor to sensitize lung cancer to cisplatin." (PMID 37165076, 2023). "It is shown that higher mRNA expression of TRPV1 was correlated to poorer OS and PFS in female lung cancer patients while only associated with poor PFS in male patients." (PMID 35620019, 2022). "All these results above suggested that TRPV1 plays a crucial role in immune‐activating functions in lung cancer, especially in LUAD." (PMID 35620019, 2022). "In conclusion, we show that TRPV1 is expressed at high levels in lung cancer and A549-DDP/5-FU resistant cells." (PMID 35402237, 2022). "Here, we aimed to assess TRPV1 as well as a potential prognostic biomarker and to explore its possibility to become a novel therapeutic target in lung cancer." (PMID 35620019, 2022). "Based on existing research on the combined application of TRPV1 agonists and corresponding antagonists in cervical cancer and lung cancer cell, it is a very meaningful work to carry out TRPV1-related therapeutic targets for the treatment of cervical cancer." (PMID 36230965, 2022). "These statistical results indicated the prognostic potential of TRPV1 in lung cancer, and the difference in TRPV1 expression leads to different prognostic potential patterns in different subtypes of lung cancer." (PMID 35620019, 2022). "Our study provides further clarification of the role of TRPV1 in modulating the sensitivity of lung cancer cells to chemotherapeutic agents and highlights its potential as a novel therapeutic target for lung cancer." (PMID 35402237, 2022). "A few years earlier, the AEA derivative Met-AEA had already been shown to exhibit anti-invasive properties on human cervical and lung cancer cells via cannabinoid receptors and TRPV1." (PMID 35277658, 2022). "In a later study, the same group found that intercellular adhesion molecule-1 (ICAM1) was upregulated by cannabidiol-elicited TRPV1-activation-mediated p42/44 activation in lung cancer cell lines A549, H358, and H460, subsequently inhibiting cell invasion." (PMID 34131404, 2021). "Recently, the expression of the cannabinoid receptors CB1 and CB2 as well as of TRPV1 was assessed in various lung cancer cell lines (A549, H358, H460) as well as primary lung cancer cells by Western blot analyses of membrane fractions." (PMID 26930716, 2016). "Cellular function and western blot experiments revealed that TRPV1 may be required for cancer cell migration in head and neck cancer and lung cancer by inhibition of PI3K/AKT and promotion of immune cell infiltration and autophage." (PMID 41535811, 2026).
lung carcinoma (continued). "Similar to the findings on lung cancer cells, the localization and expression of TRPV1 might play an important role in CBD’s anticancer activity on breast cancer cells." (PMID 35741337, 2022). "Moreover, capsaicin activates TRPV6 instead of TRPV1 to induce apoptosis in GC and lung cancer cells." (PMID 33008449, 2020). "A similar anti-invasive TRPV1-dependent impact on lung cancer cells could be proven for FAAH siRNA and the FAAH inhibitors URB597 and N-arachidonoylserotonin (AA-5HT), as well as for CBD." (PMID 31143113, 2019). "Also, we determined the correlation between TRPV1 mRNA expression levels and various clinical features, in order to better elucidate the correlation and mechanism of the function of TRPV1 in lung cancer, especially the lung cancer patients in different clinical stages." (PMID 35620019, 2022). "Therefore, CBD works as an agonist of CB1, CB2, and TRPV1 in lung cancers." (PMID 33143283, 2020). "In lung cancer, both AA-5HT and URB597 contrast tumor invasion through TIMP-1 upregulation, likely in a CB2- and TRPV1-dependent way." (PMID 31979368, 2020). "Various lung cancer cell lines (e.g., A549, H358, and H460) have been shown to express CB1, CB2, and TRPV1, which the anti-invasive function of CBD partly relies on." (PMID 33143283, 2020). "URB597 and AA-5HT were further found to decrease human lung cancer cell invasion via CB2- and TRPV1-dependent upregulation of TIMP-1." (PMID 31143113, 2019). "In a study using lung cancer cell lines, including A549, H358, and H460 NSCLC, low doses of CBD (up to 3 μM) significantly attenuated intercellular adhesion molecule-1 (ICAM-1)-dependent cell invasion via cannabinoid receptors, TRPV1, and p42/44 mitogen-activated protein kinase (MAPK)." (PMID 35741337, 2022). "Furthermore, TRPV1 overexpression induced chemoresistance through upregulation of the ABCA5 drug transporter, enhancement of HR DNA repair and activation of the p38 MAPK signaling pathway to increase IL-8 release in lung cancer A549 cells." (PMID 35402237, 2022).
myocardial ischemia (18 papers, 2006 to 2025). A disorder of cardiac function caused by insufficient blood flow to the muscle tissue of the heart. "Myocardial ischemia causes the excitation of cardiac afferent nerves, including myelinated A-delta and unmyelinated C fibers expressing transient receptor potential vanilloid 1 (TRPV1), which are associated with arrhythmogenic ventricular remodeling." (PMID 37893094, 2023). "In the myocardial ischemia reperfusion model, TRPV1 expression increased in DRG tissue after 30 min of occlusion of the coronary artery and 2 h of reperfusion." (PMID 40540176, 2025). "Both protein and phosphorylation levels of TRPV1 and the immunofluorescence intensity of TRPV1 protein expression and channel activity of TRPV1 in DRG induced by cardiac ischemia have a critical role in heart injury." (PMID 40540176, 2025). "When we applied RTX treatment directly to the DRG in our pig model of IR, we found a significant decrease in the intensity of TRPV1 expression in the primary afferents, which was correlated with decreased symptoms of cardiac ischemia." (PMID 37893094, 2023). "Histological and functional research also show that CSAN ending are mainly TRPV1 positive receptors and these afferent nerves are essential for the cardiogenic sympathoexcitatory reflex during myocardial ischemia." (PMID 35934775, 2022). "In rats subjected to 30 min of myocardial ischemia followed by 120 min reperfusion, TRPV1 mRNA was upregulated in the dorsal root ganglia (DRG) neurons." (PMID 32586044, 2020). "Previous studies have reported a cardioprotective role for TRPV1 in myocardial ischemia and reperfusion injury, in addition to attenuating cardiac hypertrophy." (PMID 32039693, 2020). "The inhibitory mechanisms of PKA and/or CaMKII via TRPV1 are unclear, but previous studies have reported a cardioprotective role for TRPV1 in myocardial ischemia and reperfusion injury." (PMID 32039693, 2020). "TRPV1 plays a protective role in myocardial ischemia via preventing LV remodeling and cardiac functional deterioration, enhancing myocardium healing and regeneration." (PMID 25152753, 2014). "5-Lipoxygenase (5-LOX) metabolites of arachidonic acid have been shown to activate cardiac sensory afferents possibly by activating TRPV1 during myocardial ischemia." (PMID 19305794, 2008). "In addition, antithrombin-98-5p has been shown to alleviate microvascular dysfunction and enhance the expression of NGF and TRPV1 in a rat myocardial ischemia/reperfusion model." (PMID 40217309, 2025). "In this study, we hypothesized that blocking TRPV1 activity would lead to an improvement in the symptoms of myocardial ischemia." (PMID 37893094, 2023). "The experiment shows that on the myocardial ischemia-reperfusion, additional activation of the spinal cord TRPV1 contributed to a severer myocardial injury; however, intrathecal administration of the TRPV1 antagonist capsazepine reduced the size of the infarct area." (PMID 34779356, 2021). "The heat-sensitive transient receptor potential vanilloid 1 (TRPV1), which is highly expressed on cardiac sensory neurons, reportedly plays a crucial role in transmitting nociceptive signals from the heart to the spinal cord during myocardial ischemia and reperfusion." (PMID 41387112, 2025). "Our future work will utilize the pharmacological antagonism of both TRPV1 and CGRP to confirm that TRPV1 and CGRP are necessary for the therapeutic effects of RTX during cardiac ischemia." (PMID 37893094, 2023). "Cardiac stress leads to increased TRPV1 levels within the DRG primary afferent cells via a cAMP-dependent signaling pathway and increased channel activity during myocardial ischemia." (PMID 37893094, 2023). "Thus, TRPV1 was speculated to play a multiple part in DM mice subjected to myocardial ischemia." (PMID 27252827, 2016).
myocardial ischemia (continued). "This possibility is supported by the finding that recovery from myocardial ischemia is compromised in TRPV1 knockout mice and proton mediated CGRP release from the heart is mediated exclusively by TRPV1." (PMID 16916451, 2006). "Previous studies have indicated that TRPV1 and its main neuropeptides calcitonin gene-related peptide (CGRP) and substance P significantly decreased in diabetic hearts, which was related to the poor recovery of cardiac function after myocardial ischemia." (PMID 27252827, 2016).